SIAH3 (siah E3 ubiquitin protein ligase family member 3)
Description:
Negative regulator of PRKN translocation to damaged mitochondria. Acts probably by destabilizing PINK1 protein, hence inhibiting PRKN targeting to dysfunctional depolarized mitochondria.
Synonyms: FLJ39203
Tractability: No criterion of Open Targets' tractability assessment is met for any kind of drug.
Gene: Protein-coding gene on chromosome 13 (45,777,242 to 45,851,753, reverse strand). Ensembl gene ENSG00000215475.
Subcellular location: Mitochondrion
Subcellular location (Human Protein Atlas): Mitochondria; Nucleoplasm
Gene Ontology:
Molecular function: protein binding; ubiquitin conjugating enzyme binding; ubiquitin protein ligase activity
Biological process: negative regulation of establishment of protein localization to mitochondrion; regulation of protein stability; proteasome-mediated ubiquitin-dependent protein catabolic process; ubiquitin-dependent protein catabolic process
Cellular component: mitochondrion; cytoplasm
Genetic constraint (gnomAD): Loss-of-function variants: 11 observed, 16.18 expected, observed/expected ratio (o/e) 0.68, 90% interval 0.43 to 1.13. The upper end of that interval is the gene's LOEUF score, 1.13, which puts it in group 4 of 6, group 1 being the genes least tolerant of losing a copy. Missense variants: 390 observed, 383.41 expected, observed/expected ratio (o/e) 1.02, 90% interval 0.94 to 1.11. Synonymous variants: 154 observed, 160.29 expected, observed/expected ratio (o/e) 0.96, 90% interval 0.84 to 1.1.
Homologues: Orthologues: chimpanzee SIAH3 (99% identical), macaque SIAH3 (98% identical), dog SIAH3 (94% identical), guinea pig SIAH3 (93% identical), pig SIAH3 (93% identical), rabbit SIAH3 (92% identical), mouse Siah3 (90% identical), rat Siah3 (89% identical). Paralogues in human: SIAH2 (41% identical), SIAH1 (40% identical), ZSWIM9 (17% identical).
Diseases named in the same sentence as SIAH3 in open-access papers:
SIAH3 is named in the same sentence as 17 diseases in open-access papers, as found by Europe PMC text mining. Sharing a sentence is not in itself a finding about the gene and the disease. The quoted sentences say what the papers report.
lung carcinoma (1 paper, 2025). "DepMap data suggest that inhibition of SIAH3 results in proliferation in PDAC cells and in RAS-driven lung cancer cells, and TCGA clinical samples show a progressive decrease in SIAH3 expression in advanced PDAC stages." (PMID 40243415, 2025).
pancreatic adenocarcinoma (1 paper, 2025). "TCGA data of the entire PAAD (pancreatic adenocarcinoma) cohort showed SIAH3 expression to be decreased in advanced cancer stages (p < 0.01), suggesting a possible correlation with disease progression." (PMID 40243415, 2025). "Kaplan–Meier analyses show that high expression of SIAH3 (upper tertile) is associated with significantly improved overall survival in non-metastatic PDAC patients in both the TCGA and the CPTAC pancreatic adenocarcinoma cohorts." (PMID 40243415, 2025). "Data from the Tumor Cancer Genome Atlas (TCGA) cohort showed SIAH3 to be down-regulated in multiple cancers, including pancreatic adenocarcinoma (PAAD), compared to normal non-cancerous tissues." (PMID 40243415, 2025).
pancreatic cancer (1 paper, 2025). "Additional analysis of the DepMap portal revealed that siRNA knockdown of SIAH3 resulted in a net increase in cell proliferation across all 15 pancreatic cancer cell lines." (PMID 40243415, 2025). "As pancreatic cancer is primarily driven by the overactivation of the RAS pathway, and the SIAH family has a known role in the hypoxia signaling cascade, we found these changes in SIAH3 expression to be especially interesting." (PMID 40243415, 2025).
proteinopathy (1 paper, 2022). "Because PD is considered a proteinopathy, we investigated whether SIAH3 can aggregate in PD." (PMID 36307912, 2022).
stress-related disorder (1 paper, 2021). Stress-related disorders are mental health disorders that are a result of an atypical response to both short and long-term anxiety due to physical, mental, or emotional stress. "Since SIAH3 has not been previously associated with ELA or any stress-related disorders, it is important to validate this finding with future independent studies." (PMID 33542190, 2021).
cancer (2 papers, 2017 to 2025). A tumor composed of atypical neoplastic, often pleomorphic cells that invade other tissues. "This limited investigation, performed as a proof-of-concept for the use of chronic hypercapnia to screen for cancer-related targets, validated SIAH3 as a hypercapnia-effected target and observed an association with clinical outcomes." (PMID 40243415, 2025). "It is still unclear whether SIAH3 holds any mechanistic and clinical impact on cancer progression or whether it serves only as an associated prognostic factor and further mechanistic studies should be undertaken to elucidate its role." (PMID 40243415, 2025). "The discovery of SIAH3’s increased expression in a subset of human cancer cells presents an interesting opportunity for novel drug discovery." (PMID 28784114, 2017). "We find that SIAH1 and SIAH2 are expressed in all human epithelial cell lines examined thus far, while SIAH3 is only expressed in a limited subset of cancer cell lines." (PMID 28784114, 2017). "This suggests that rapidly replicating cancer cell lines exhibit low expression levels of SIAH3." (PMID 40243415, 2025). "SIAH3 appears to be an attractive target for further investigation as its active homologs, SIAH1 and SIAH2, are known to be downstream effectors of the KRAS pathway and have been shown to be associated with cancer progression and poor prognosis in multiple cancers." (PMID 40243415, 2025). "Since the RAS-MEK-MAPK pathway is an important regulator of cell proliferation in cancer cells, we analyzed data from the Cancer Cell Line Encyclopedia (CCLE) for correlation between SIAH3 expression and cellular growth rates in 506 cancer cell lines." (PMID 40243415, 2025). "Additional work will be conducted to examine the interplay between SIAH3 and SIAH1/SIAH2 in oncogenic K-RAS-driven human cancers in the future." (PMID 28784114, 2017). "By taking advantage of nonfunctional SIAH3 as a putative endogenous SIAH inhibitor, we may be able to develop a novel anti-SIAH1 and anti-SIAH2 strategy by utilizing SIAH3 expression to antagonize oncogenic K-RAS-driven metastatic human cancer cells." (PMID 28784114, 2017).
inflammation (1 paper, 2024). Aberrant reaction of the microcirculation characterized by movement of fluid and leukocytes from the blood into extravascular tissues. "It was reported that Siah3/NF-κB signaling pathway is activated in the cochlea and participates in the formation of cochlear inflammation after noise injury, And it has also been shown that expression of NF-κB increased in the utricle after cisplatin injury." (PMID 39764513, 2024).
neurodegenerative disease (1 paper, 2019). A disorder of the central nervous system characterized by gradual and progressive loss of neural tissue and neurologic function. "Our findings suggest that SIAH3 gene, as a novel genetic factor, may be involved in the pathogenesis of neurodegenerative diseases." (PMID 31711042, 2019). "The biological function of SIAH3 in mitochondrial dysfunction may have relevance for the pathogenesis of neurodegenerative diseases, which merits further investigation." (PMID 31711042, 2019). "Our findings indicated that SIAH3 gene may have potential influence on the pathogenesis of neurodegenerative diseases." (PMID 31711042, 2019). "Thus, we hypothesized that SIAH3 can affect the PINK1/Parkin mitophagy by inhibiting the accumulation of PINK1 in the damaged mitochondria, subsequently leading to mitochondrial dysfunction involved in the pathology and pathogenesis of neurodegenerative diseases." (PMID 31711042, 2019).
SIAH3 also shares sentences with these, for which no sentence is quoted: alcohol dependence (2 papers); Alzheimer disease (2); Anxiety (2); dementia (2); depression (2); encephalomyopathy (2); pancreatic ductal adenocarcinoma (1); renal fibrosis (1); tumor (1).